TIPE3 (TNF alpha induced protein 8 like 3)
Diseases named in the same sentence as TIPE3 in open-access papers (continued):
Sharing a sentence is not in itself a finding about the gene and the disease.
cancer (19 papers, 2017 to 2025). A tumor composed of atypical neoplastic, often pleomorphic cells that invade other tissues. "TIPE3 acts as a transfer protein for secondary lipid messengers and is associated with the progression of different types of cancers." (PMID 40280943, 2025). "Shared interaction residues offer insights for designing potent inhibitors against TIPE3-associated cancers." (PMID 38727307, 2024). "Nevertheless, the underlying mechanisms for these contradictory roles of TIPE3 in different cancers remain to be determined." (PMID 30217224, 2018). "Except for CESC, the TIPE3 mRNA levels were found to be negatively related to the methylation levels of cg05905176 in five of the six cancers, implying that TIPE3 downregulation in human cancers is associated with its CGI hypermethylation." (PMID 30217224, 2018). "TIPE3 expression has been reported to be upregulated in several cancers, including lung, breast, and colon cancer." (PMID 40280943, 2025). "Accumulating evidence has demonstrated the vital importance of TIPE3 in various biological processes, especially in the development and progression of cancer." (PMID 40904408, 2025). "TIPE2, a member of the same family, suppresses OVCA metastasis and epithelial–mesenchymal transition by interacting with SMAD2, indicating that our findings need to be experimentally validated for the role of TIPE3 in promoting cancer." (PMID 40343258, 2025). "TIPE3 is highly upregulated in several human cancers and has been established to play an important role in tumor progression." (PMID 38727307, 2024). "TIPE3 is highly upregulated in several human cancers and has been established to significantly promote tumor cell proliferation, migration, and invasion and inhibit the apoptosis of cancer cells." (PMID 38727307, 2024). "Using clinical samples from 110 CRC patients, we found the TIPE3 protein to be upregulated in CRC cancer tissues and to be significantly correlated with patients’ OS rate." (PMID 36755222, 2023). "Overall, the expression of TIPE3 in cancer tissues was significantly higher than in adjacent normal tissues." (PMID 36755222, 2023). "Colony formation assay showed that single cancer cell survival and proliferation abilities were attenuated by restoring TIPE3." (PMID 37024453, 2023). "The expression level of TIPE3 in the cancer and adjacent tissues of 110 CRC patients was detected by immunohistochemistry (IHC)." (PMID 36755222, 2023). "After IHC scoring, the median score was taken as the cutoff value, and the cancer tissues were divided into a low TIPE3 expression group (≤4.9; n = 34) and a high TIPE3 expression group (>4.9; n = 76)." (PMID 36755222, 2023). "TIPE3 hypermethylation in the CpG island (CGI) has frequently been observed and contributes to the silencing of TIPE3 expression in many cancer types, including NPC." (PMID 35565251, 2022). "Among all the differentially methylated CpG sites, cg05905176, cg00063471, cg18588323, and cg06813578 made up the major proportion, indicating that TIPE3 hypermethylation is a common event in human cancers." (PMID 30217224, 2018). "Collectively, our results suggested that the downregulation of TIPE3 was related to its CGI hypermethylation, and epigenetic silencing of TIPE3 was a common event in human cancer." (PMID 30217224, 2018). "It has been recognized that mouse TIPE3 serves as a transfer protein for lipid second messengers to promote cancers, whereas the potential roles of human TIPE3 in NSCLC remain to be clarified." (PMID 29510688, 2018). "Here, we found that the TIPE3 was hypermethylated and the mRNA was downregulated in several human cancers, including NPC." (PMID 30217224, 2018). "It was found that the level of TIPE1 and TIPE3 was decreased in poorly cohesive carcinoma compared with adjacent non‐tumour tissue." (PMID 28994231, 2018). "TIPE3 (TNFAIP8L3) is the transfer protein of phosphoinositide second messengers that promote cancer." (PMID 28388580, 2017).
cancer (continued). "TIPE3 can induce cancer cell malignant transformation by promoting the activation of the PI3K-AKT pathway." (PMID 28388580, 2017). "Recent studies show that TIPE3 is expressed in several human organs and is highly upregulated in several human carcinomas including lung cancer, esophageal cancer, cervical cancer, colon adenocarcinoma, and so on." (PMID 28388580, 2017). "Previous research has showed that TIPE3 is highly expressed in most human carcinoma cell lines and promotes tumor malignant transformation." (PMID 28388580, 2017). "Several studies have demonstrated that TIPE3 is a driver gene in various cancers." (PMID 40280943, 2025). "Whether inhibiting the function of TIPE3 with small molecules could be an effective strategy for cancer treatment is unknown." (PMID 38727307, 2024). "Subsequently, researchers validated the oncogenic function of TIPE3 in a variety of human cancers." (PMID 38727307, 2024). "A statistical analysis showed that 69.10% (76/110) and 30.90% (34/110) of cases exhibited high and low TIPE3 expression levels in cancer tissues, respectively, while 34.55% (38/110) and 65.45% (72/110) of cases exhibited high and low TIPE3 expressions in adjacent normal tissues, respectively." (PMID 36755222, 2023). "Also, to demonstrate its application in virtual screening, we have developed a pipeline and screened it over two cancer-related therapeutic targets, TIPE3 and the PD-L1 dimer, as proof-of-concept applications." (PMID 37375246, 2023). "Our study found that the TIPE3 expression in CRC cancer tissues was significantly higher than in adjacent normal tissues, which may be related to the fact that TIPE3 can promote the occurrence and development of tumors." (PMID 36755222, 2023). "Collectively, our work reveals that TIPE3 plays critical role in maintaining mitochondrial stress and cancer cell progression in HNSCC, which might be a potential therapeutic target for HNSCC patients." (PMID 37024453, 2023). "In particular, strong expression of TIPE3 was detected on protrusion of both H1975 and A549 cells, suggesting the potential link between the plasma membrane expression of TIPE3 and the viability of cancer cells." (PMID 29510688, 2018). "However, in some samples TIPE3 was pervasively expressed in the cytoplasm of cancer cells, while in others TIPE3 was mainly expressed in the plasma membrane of cancer cells." (PMID 29510688, 2018). "We showed that TIPE3 was broadly expressed in cancer tissues of patients with NSCLC." (PMID 29510688, 2018). "Notably, marked increase in TIPE3 expression was detected in human cancer tissues including cervical, colon, lung and esophageal." (PMID 29510688, 2018). "Thus, inhibiting the function of TIPE3 is expected to be an effective strategy against cancer." (PMID 38727307, 2024). "Different from the oncogenic role of TIPE3, TIPE2 predominantly functions as a tumor suppressor in various types of cancers." (PMID 40904408, 2025). "In majority cancers, TIPE and TIPE3 were realized as anti-apoptotic and pro-survival proteins, while TIPE1 and TIPE2 were considered to be potential pro-apoptotic and anti-tumor molecules." (PMID 37024453, 2023). "Most reports believe that TNFAIP8 and TIPE3 have antiapoptotic and tumorigenesis effects, while TIPE1 and TIPE2 have pro-apoptotic and antitumor effects in most cancers." (PMID 34925463, 2021). "We found that TIPE3 CpG island (CGI) was hypermethylated and its mRNA levels were downregulated in many cancers, including NPC." (PMID 30217224, 2018). "In lung cancer, TIPE3 was found to be upregulated and could activate the AKT/ERK1/2-GSK3β-b-catenin/Snail pathway, enhancing the migration of cancer cells." (PMID 38727307, 2024). "We found that the levels of TIPE3 expression were higher in MDA-MB-231 and BT549 cells which were considered as more invasive cancer cells than MCF-7 and MDA-MB-468 cells, suggesting that TIPE3 might be associated with cancer migration and invasion." (PMID 28388580, 2017).
cancer (continued). "At the same time, we investigated the relationship between the TIPE3 expression level and tumor immune invasion: IHC was used to detect the positive cell numbers of CD8+ T cells, CD20+ B cells, and CD66b+ neutrophils in the cancer and adjacent tissues of 110 CRC patients." (PMID 36755222, 2023). "In the present study, we found that ectopic expression of TIPE3 significantly suppressed NPC cell proliferation and invasion in vitro and in vivo, indicating that TIPE3 might act as a tumor suppressor in NPC and play a dual role in cancer progression." (PMID 30217224, 2018).
tumor (19 papers, 2017 to 2025). "Increased TIPE3 expression is associated with regulating apoptosis, promoting inflammatory responses, and influencing the tumor microenvironment of CRC." (PMID 40280943, 2025). "Taken together, our results suggest the TIPE3 expression may be associated with tumor-immune infiltration." (PMID 36755222, 2023). "TIPE3 expression has been found to be significantly elevated in a variety of tumor cells and tissues." (PMID 40904408, 2025). "For example, TIPE3 triggers tumor progression by regulating the metabolism of phosphoinositide second messengers." (PMID 40280943, 2025). "TIPE3 primarily functions as a tumor promoter during the processes of tumorigenesis and tumor progression." (PMID 40904408, 2025). "In vivo experiments in mice suggested that TIPE3 inhibited apoptosis of tumor cells and promoted macrophage M2-type polarization in tumor tissues by up-regulating the protein expression of USP19." (PMID 40280943, 2025). "qPCR analysis of TIPE3 expression in tumor tissues of CRC patients revealed that compared with normal tissue, tumor tissues showed markedly elevated expression of TIPE3." (PMID 40280943, 2025). "IHC revealed that TIPE3 expression was substantially higher in tumor tissues than in normal tissues." (PMID 40280943, 2025). "Consistent with the previous research, the present study found that TIPE3 expression was significantly increased in LUAD tumor tissues compared with adjacent normal tissues." (PMID 40904408, 2025). "Here, we report three potential small-molecule inhibitors of TIPE3 with potent in vitro anti-tumor activities." (PMID 38727307, 2024). "Given that TIPE3 has an important and common regulatory role in the initiation and progression of multiple cancers, an effective broad-spectrum anti-tumor therapeutic strategy targeting TIPE3 using small-molecule inhibitors is revealed." (PMID 38727307, 2024). "During the correlation analysis between the TIPE3 expression and clinicopathological factors, the TIPE3 expression in tumor tissues was significantly correlated with survival status (p = 0.005) and survival time (p = 0.006)." (PMID 36755222, 2023). "The expression of TIPE3 in tumor tissues is significantly higher than in adjacent normal tissues, and it is significantly correlated with the survival rate of patients in tumor tissues (p = 0.0038) and adjacent normal tissues (p<0.0001)." (PMID 36755222, 2023). "In this work, we mainly used clinical/surgical specimens, focusing on the correlation between the TIPE3 expression and tumor-immune infiltration and the prognosis of CRC patients." (PMID 36755222, 2023). "Here, downregulation of TIPE3 due to its promoter hypermethylation was identified to be critical in balancing tumor growth and apoptosis during HNSCC progression." (PMID 37024453, 2023). "The lymph nodes in the TIPE3 overexpression group showed smaller volumes and fewer pan-cytokeratin-positive tumor cells than those in the vector group." (PMID 37024453, 2023). "Then, the methylation alterations of 28 CG probes in TIPE3 genome between HNSCC tumor and normal tissues were examined." (PMID 37024453, 2023). "Of these genes, TNFAIP8, TIPE1, and TIPE3 are known to greatly influence tumor occurrence and development, while TIPE2 is mainly involved in innate immunity and acquired immunity." (PMID 36118167, 2022). "As a phosphoinositide transfer protein, TIPE3 is highly expressed in tumor tissues of patients with lung and esophageal cancer possibly binding to phosphoinositides to promote tumor formation." (PMID 36118167, 2022). "TIPE and TIPE3 had been confirmed to possess a carcinogenic effect in tumor development, while TIPE2 was proved to play opposite roles in cell death and tumorigenesis." (PMID 34188681, 2021). "Immunohistochemistry showed that TIPE3, especially plasma membrane-localizing TIPE3, was obviously increased in the tumor tissue sections from mice received NSCLC cells overexpressing TIPE3 compared with those from mice received control NSCLC cells." (PMID 29510688, 2018).
tumor (continued). "Mice received A549 cells overexpressing TIPE3 showed a marked increase in tumor growth, as confirmed by increased tumor volume and weight." (PMID 29510688, 2018). "The MTT, colony formation, Transwell migration and invasion assays, and xenograft tumor growth and lung metastatic colonization models were used to identify the functions of TIPE3 on NPC cells." (PMID 30217224, 2018). "TIPE3 acts as a tumor suppressor in NPC, providing a further insight into NPC progression and representing a potential prognostic biomarker for NPC." (PMID 30217224, 2018). "Next, we established subcutaneous xenograft tumor models in nude mice using A549 cells transfected with recombinant lentivirus expressing C-terminal flag-tagged human TIPE3." (PMID 29510688, 2018). "NSCLC cells, in which TIPE3 with C-terminal flag was stably transfected, were inoculated into mice to establish xenograft tumors, the tumor growth and the expression of TIPE3 in tumor tissues were examined." (PMID 29510688, 2018). "As a result, the final tumor mean volume and weight of TIPE3 group was significantly increased compared with Ctrl group." (PMID 28388580, 2017). "We found that TIPE3 was significantly upregulated in the majority of tumor sections compared with adjacent non-tumor section from the same patients (Figure 1A1–1A3, P < 0.001)." (PMID 28388580, 2017). "The results from WB and IHC showed that TIPE3 protein expression was higher in tumor tissues with TIPE3 treatment." (PMID 28388580, 2017). "In addition, consistent with the results of the experiments in LoVo and SW480 cells, TIPE3 also increased the protein expression level of USP19 in mouse tumor tissues." (PMID 40280943, 2025). "TIPE3 may enhance the resistance of tumor cells to L-OHP at multiple levels, thereby affecting the efficacy of chemotherapeutic drugs." (PMID 40280943, 2025). "Previous research also found that membrane-located TIPE3 promotes the proliferation and metastasis of NSCLC cells, and the Wnt signaling may contribute to TIPE3-induced tumor progression." (PMID 40904408, 2025). "Moreover, USP19 (induced by TIPE3) triggers macrophage M2 polarization in the tumor microenvironment, inhibiting the immune response and affecting autophagy and apoptosis of tumor cells." (PMID 40280943, 2025). "Meanwhile, TUNEL staining showed that TIPE3 overexpression significantly inhibited the apoptotic damage of tumor tissues induced by L-OHP, which might help tumor cells escape from the injuries caused by chemotherapeutic drugs." (PMID 40280943, 2025). "This suggests that TIPE3 promotes M2 macrophage polarization in mouse tumor tissues." (PMID 40280943, 2025). "Finally, the biological roles of TIPE3 in HNSCC cells in vivo were determined using a subcutaneous tumor growth and axillary lymph node metastasis nude mice model." (PMID 37024453, 2023). "Inhibiting either PGAM5 or DRP1 activity rescued the tumor suppression effect induced by TIPE3." (PMID 37024453, 2023). "To validate whether TIPE3 exerted the tumor suppression effect via PGAM5, we transiently knocked down PGAM5 expressions in TIPE3 or vector overexpression HNSCC cells." (PMID 37024453, 2023). "Univariate regression analysis showed that the expression of TIPE3 and the number of CD66b+ neutrophils were risk factors for the OS of CRC patients; and the number of CD8+ T cells, the number of CD20+ B cells, and tumor grade were protective factors for the OS of CRC patients." (PMID 36755222, 2023). "We confirmed the downregulation of TIPE3 via promoter hypermethylation in tumor tissues might be a critical event during HNSCC tumorigenesis." (PMID 37024453, 2023). "NPC patients with low TIPE3 CGI methylation levels were at low risk of treatment failure, which might be caused by the tumor suppression effects of TIPE3." (PMID 30217224, 2018).